TMED9 (transmembrane p24 trafficking protein 9)
Description:
Appears to be involved in vesicular protein trafficking, mainly in the early secretory pathway. In COPI vesicle-mediated retrograde transport involved in the coatomer recruitment to membranes of the early secretory pathway. Increases coatomer-dependent activity of ARFGAP2. Thought to play a crucial role in the specific retention of p24 complexes in cis-Golgi membranes; specifically contributes to the coupled localization of TMED2 and TMED10 in the cis-Golgi network. May be involved in organization of intracellular membranes, such as of the ER-Golgi intermediate compartment and the Golgi apparatus. Involved in ER localization of PTPN2 isoform PTPB.
Synonyms: p24alpha2; HSGP25L2G; p24a2; GMP25; p25
Tractability: Small molecule: a structure with a bound ligand is known. Antibody: UniProt predicts a signal peptide or a membrane-spanning region. PROTAC: ubiquitination databases record sites on it; its protein half-life has been measured.
Gene: Protein-coding gene on chromosome 5 (177,592,195 to 177,597,242, forward strand). Ensembl gene ENSG00000184840.
Subcellular location: Endoplasmic reticulum membrane; Golgi apparatus, cis-Golgi network membrane; Endoplasmic reticulum-Golgi intermediate compartment membrane; Golgi apparatus, trans-Golgi network membrane
Pathways (Reactome):
Vesicle-mediated transport: COPI-dependent Golgi-to-ER retrograde traffic; COPI-mediated anterograde transport
Gene Ontology:
Molecular function: protein binding; syntaxin binding
Biological process: COPI coating of Golgi vesicle; Golgi organization; endoplasmic reticulum to Golgi vesicle-mediated transport
Cellular component: endoplasmic reticulum; endoplasmic reticulum-Golgi intermediate compartment; extracellular exosome; Golgi apparatus; endoplasmic reticulum membrane; endoplasmic reticulum-Golgi intermediate compartment membrane; Golgi membrane; trans-Golgi network transport vesicle; transport vesicle; synaptic vesicle
Genetic constraint (gnomAD): Loss-of-function variants: 22 observed, 29.81 expected, observed/expected ratio (o/e) 0.74, 90% interval 0.53 to 1.05. The upper end of that interval is the gene's LOEUF score, 1.05, which puts it in group 4 of 6, group 1 being the genes least tolerant of losing a copy. Missense variants: 251 observed, 313.17 expected, observed/expected ratio (o/e) 0.8, 90% interval 0.72 to 0.89. Synonymous variants: 146 observed, 126.02 expected, observed/expected ratio (o/e) 1.16, 90% interval 1.01 to 1.33.
Homologues: Orthologues: chimpanzee TMED9 (99% identical), macaque TMED9 (99% identical), dog TMED9 (94% identical), guinea pig TMED9 (94% identical), mouse Tmed9 (94% identical), pig TMED9 (93% identical), rat Tmed9 (93% identical), tropical clawed frog tmed9 (79% identical), zebrafish tmed9 (78% identical), Caenorhabditis elegans tmed-4 (63% identical), Drosophila melanogaster p24-1 (20% identical). Paralogues in human: TMED4 (74% identical), TMED10 (31% identical), TMED7 (25% identical), TMED2 (23% identical), TMED3 (22% identical), TMED1 (21% identical), TMED5 (20% identical), TMED6 (20% identical).
Diseases named in the same sentence as TMED9 in open-access papers:
TMED9 is named in the same sentence as 42 diseases in open-access papers, as found by Europe PMC text mining. Sharing a sentence is not in itself a finding about the gene and the disease. The quoted sentences say what the papers report.
colon cancer (7 papers, 2019 to 2025). "Lastly, TMED9 was shown to mediate colon cancer metastases by activating the GLI1, CNIH4 and TGFA regulatory pathway and opposing TMED3-WNT-TCF signaling." (PMID 40497947, 2025). "Studies on colon cancer have highlighted the involvement of TMED9 in driving a pro-metastatic state in colon cancer models." (PMID 40497947, 2025). "TMED9 drives colon cancer metastasis via the CNIH4/TGFα/GLI pathway, inducing EMT and enhancing migration/invasion." (PMID 41373732, 2025). "Researches indicated that CNIH4 potentially increases colon cancer cell metastatic activity by forming a positive feedback loop with TMED9, GLI1, and TGFα." (PMID 37062068, 2023). "A relevant study confirmed that CNIH4 increased the metastatic activity in patients with colon cancer by forming a positive feedback loop involving TMED9, GLI1, and TGFα." (PMID 37062068, 2023). "In contrast, TMED3 was identified as a tumor suppressor in colon cancer and proposed to inhibit metastasis by repressing TMED9." (PMID 33888099, 2021). "The requirement of TMED9 for distant metastases was recapitulated in primary human colon cancer CC36lacZ cells and in the human colon cancer cell line LS174TlacZ." (PMID 31253868, 2019). "Analyses in three colon cancer cell types highlight a TMED9-dependent gene set that includes CNIH4, a member of the CORNICHON family of TGFα exporters." (PMID 31253868, 2019). "TMED9 antagonizes TMED3 function through promoting colon cancer metastases." (PMID 35805075, 2022). "When TMED3 was knocked down in colon cancer cells, TMED9 was upregulated more than twofold." (PMID 31878985, 2019). "Here, we provide evidence that a critical mechanism in the positive control of pro-metastatic states, and the resulting distant metastases, in human colon cancer cells is regulated protein secretion, as highlighted by the function of the protein secretion cargo selector TMED9." (PMID 31253868, 2019). "Although the roles of TMED9 and TMED3 in HCC differed from those in colon cancer, how the interaction between TMED9 and TMED3 promotes HCC progression remains for further evaluation." (PMID 33888099, 2021). "We propose that antagonistic secretion-transcription loops gated by TMED9 and TMED3 represent a key modulatory network for the control of the number of colon cancer metastatic cells." (PMID 31253868, 2019). "We propose that primary colon cancer cells can transition between two states characterized by secretion-transcription regulatory loops gated by TMED3 and TMED9 that modulate their metastatic proclivities." (PMID 31253868, 2019). "TMED9 and TMED3 play a role in this metastatic transition with their activities that balance each other to determine metastatic outcomes of colon cancer cells and control, in opposite manners, a global gene cohort that includes multiple factors implicated in the regulation of metastases." (PMID 35805075, 2022). "Moreover, WNT-TCF inhibits TMED9, which, in turn, represses WNT-TCF pathway components and drives CNIH4/TGFα/GLI signaling, thus promoting colon cancer metastases." (PMID 35805075, 2022). "Opposite roles of TMED9 and TMED3 in regulating the progression of colon cancer were reported." (PMID 33888099, 2021). "Although TMED9 has not been investigated in other cancers, in colon cancer it functions as an oncogene." (PMID 31878985, 2019). "However, the oncogenic role of TMED9 was only identified in colon cancer, but not in other cancer types." (PMID 33888099, 2021).
breast carcinoma (4 papers, 2022 to 2025). "Recent studies indicate that TMED9 overexpression in ovarian cancer correlates with poor overall survival, while in breast cancer, high TMED9 expression is associated with enhanced tumor proliferation and migratory capacity." (PMID 40124371, 2025). "TMED9 is upregulated in breast cancer, HCC, ovarian cancer, and gliomas, correlating with advanced tumor stages, metastasis, and poor survival." (PMID 41373732, 2025). "In cancer, the overexpression of TMED9 correlates with the progression and poor prognosis of several cancers, including ovarian cancer, hepatocellular carcinoma, and breast cancer." (PMID 40124371, 2025). "Analysis of collected samples from multiple cohorts and in vitro experiments revealed that High TMED9 expression in breast cancer patients encouraged the growth and migration of breast cancer cells and predicted a poor prognosis." (PMID 37928880, 2023). "Interestingly, elevated TMED2 and TMED9 expression levels in breast cancer patients were identified as poor prognostic factors." (PMID 35754792, 2022).
glioma (3 papers, 2025). A benign or malignant brain and spinal cord tumor that arises from glial cells (astrocytes, oligodendrocytes, ependymal cells). "Our findings reveal that TMED9 is significantly overexpressed in various tumor tissues and is associated with poor prognosis in cancers such as glioblastoma and lower-grade gliomas." (PMID 40124371, 2025). "Our findings demonstrate that TMED9 expression is upregulated in glioma and that this upregulation is associated with poor patient survival." (PMID 40497947, 2025). "In several additional glioma datasets, we observed a significant association between high TMED9 expression and poor prognosis." (PMID 40124371, 2025). "In multiple glioma datasets, we observed that high TMED9 expression was significantly associated with poor prognosis." (PMID 40124371, 2025). "Lastly, to demonstrate the broad applicability of our findings, we targeted TMED9 in pediatric glioma cells and showed efficient inhibition of various oncogenic functions." (PMID 40497947, 2025). "This expression pattern suggests that TMED9 plays a crucial role in the glioma immune microenvironment, particularly in the interactions between tumor cells and immune cells." (PMID 40124371, 2025). "Single-cell analysis revealed that TMED9 is predominantly expressed in the malignant cells and monocytes/macrophages of gliomas." (PMID 40124371, 2025). "Future research should focus on elucidating TMED9’s mechanistic pathways and validating its role in clinical settings to enhance glioma treatment strategies." (PMID 40124371, 2025). "The emerging findings associating TMED9 with GBM development and aggressiveness motivated us to study the potential role of TMED9 in the glioma stem cell population." (PMID 40497947, 2025). "In conclusion, our findings demonstrate an essential oncogenic role for TMED9 in both adults and pediatric glial tumors." (PMID 40497947, 2025). "Our study identifies TMED9 targeting by silencing or the small molecule BRD4780 as a promising therapeutic approach to combat glioma aggressiveness and improve patient outcomes." (PMID 40497947, 2025). "An evaluation of the relationship between TMED9 expression and glioma immunotherapy indicated that TMED9 was more highly expressed in the progressive disease group than in the partial or complete response groups." (PMID 40124371, 2025). "In this study, we explored the therapeutic potential of genetic and pharmacologic inhibition of the cargo receptor TMED9 in glial tumor models." (PMID 40497947, 2025). "Expression profile data from multiple datasets confirmed the significant upregulation of TMED9 in glioma." (PMID 40124371, 2025). "This study aims to provide a comprehensive analysis of the role of TMED9 in various cancers and its impact on the clinical significance and prognostic value of glioma." (PMID 40124371, 2025). "Multivariate Cox analysis further identified TMED9 as an independent prognostic factor for glioma, confirming its potential as a prognostic marker." (PMID 40124371, 2025). "Given the notably high expression of TMED9 in glioma and its impact on patient prognosis, we focused on analyzing the relationship between TMED9 and glioma." (PMID 40124371, 2025). "Future studies should further investigate the specific mechanisms by which TMED9 operates in glioma." (PMID 40124371, 2025). "Overall, these findings indicate that TMED9 is significantly overexpressed in gliomas with greater malignancy." (PMID 40124371, 2025). "Among these, the drug AH 6809 was recognized as a potential small molecule capable of rectifying the biological effects induced by dysregulated TMED9 expression in gliomas." (PMID 40124371, 2025). "Knockdown of TMED9 led to reduced migration and invasion in glioma cell lines." (PMID 40124371, 2025). "Knocking down TMED9 in glioma cell lines significantly reduced the migration and invasion abilities of these cells, indicating that TMED9 may promote the biological characteristics of glioma." (PMID 40124371, 2025).
glioma (continued). "Single-gene localization analysis revealed that TMED9 expression is similar in tumor cells and macrophages, suggesting that within the context of glioma, TMED9 may primarily be expressed by these cell types." (PMID 40124371, 2025). "Concurrently, clinical trials to validate TMED9 as a therapeutic target may enhance glioma treatment efficacy." (PMID 40124371, 2025). "In addition to TMED2, a recent bioinformatics study demonstrated a positive correlation between the expression of TMED4 and TMED9 and glioma aggressiveness and a negative association with patient prognosis." (PMID 40497947, 2025). "Similarly, elevated TMED9 levels were observed in grade 4 gliomas compared to grade 2 or 3 gliomas." (PMID 40497947, 2025). "Notably, high TMED9 expression was significantly negatively correlated with the stemness score of glioma, suggesting that TMED9 may contribute to chemotherapy resistance in glioma by inhibiting tumor stem cell properties." (PMID 40124371, 2025). "After merging expression profiles and clinical data from GBM and LGG, we found that high TMED9 expression correlated significantly with shorter OS, DSS, and PFI in glioma patients." (PMID 40124371, 2025).
proteinopathies (3 papers, 2022 to 2024). "Third, our work has broader implications, as TMED9-mediated entrapment of misfolded cargos likely causes many toxic proteinopathies, including uromodulin-associated kidney disease and retinitis pigmentosa, a form of blindness." (PMID 39303030, 2024). "We identified residues responsible for cargo recognition in the GOLD domain of TMED9, which may provide clues for identifying additional toxic proteinopathies that share the same mechanism of entrapment in the early secretory pathway." (PMID 39303030, 2024). "We have reported that TM emp24 domain protein 9 (TMED9) is necessary for MUC1-fs entrapment in MKD, as well as the pathogenesis of additional genetically defined proteinopathies that affect many tissues such as the kidney and the eye." (PMID 39303030, 2024).
glioblastoma (2 papers, 2019 to 2025). The most malignant astrocytic tumor (WHO grade IV). "Using this assay, TMED9 was shown to be similarly required for the migration of human U251 glioblastoma cells, a tumor cell type that readily invades the brain parenchyma used here to test whether TMED9 kd might also affect other tumor types." (PMID 31253868, 2019).
hepatocellular carcinoma (2 papers, 2022 to 2025). A malignant tumor that arises from hepatocytes. "The role of TMED9 in hepatocellular carcinoma is also increasingly recognized, as its expression levels correlate with tumor vascular invasion and unfavorable prognosis." (PMID 40124371, 2025). "Also, highly expressed TMED9 significantly affected vascular invasion and poor prognosis in patients with hepatocellular carcinoma (Yang Y.-C." (PMID 35754792, 2022). "Besides, the high expression of TMED9 might promote the proliferation of cancer cells by inhibiting autophagy and predict poor prognosis in hepatocellular carcinoma (HCC) and colon cancer." (PMID 35754792, 2022).
astrocytic tumor (1 paper, 2025). A glial tumor of the brain or spinal cord showing astrocytic differentiation. "To examine the potential role of TMED9 in GBM and provide support for the therapeutic applicability of the small molecule BRD4780, we analyzed available databases and investigated TMED9 expression in various brain tissues and astrocytic tumors." (PMID 40497947, 2025).
brain cancer (1 paper, 2025). A primary or metastatic malignant neoplasm affecting the brain. "Furthermore, high levels of TMED9 expression were observed in tumor cell lines, including kidney cancer, brain cancer, and myeloma." (PMID 40124371, 2025).
brain tumors (1 paper, 2025). "Collectively, our study identifies TMED9 inhibition as a promising therapeutic approach that impairs the tumorigenesis and aggressiveness of brain tumors, with high efficacy against the tumor stem cell population." (PMID 40497947, 2025). "Importantly, this is the first time, to the best of our knowledge, that TMED9 is shown to play a major role in the function and tumorigenesis of brain tumor cancer stem cells and pediatric brain tumors." (PMID 40497947, 2025).
cervical squamous cell carcinoma (1 paper, 2025). A squamous cell carcinoma arising from the cervical epithelium. "Univariate Cox regression analysis demonstrated that high TMED9 expression was significantly associated with poor OS in cervical squamous cell carcinoma and endocervical adenocarcinoma (CESC), GBM, HNSC, KIRC, LGG, and UVM." (PMID 40124371, 2025).
colorectal cancer (1 paper, 2024). A primary or metastatic malignant neoplasm that affects the colon or rectum. "Additionally, a positive correlation was identified between TMED1 and other members of the TMED family (TMED2, TMED4, TMED9, and TMED10) in colorectal cancer." (PMID 38392302, 2024).
head and neck squamous cell carcinoma (1 paper, 2025). A squamous cell carcinoma that arises from any of the following anatomic sites: lip and oral cavity, nasal cavity, paranasal sinuses, pharynx, larynx, and salivary glands. "Notably, we observed significantly high TMED9 expression during the M1 stage of head and neck squamous cell carcinoma (HNSC), KIRC, and mesothelioma (MESO), while significantly low expression was evident in the M1 stage of LUAD, suggesting a potential association with tumor metastasis." (PMID 40124371, 2025).
mild cognitive impairment (1 paper, 2025). "Numerous TMED proteins have been shown to be dysregulated in mild cognitive impairment (MCI) and AD brains: While TMED5 expression increases in the AD parietal cortex, expression of both TMED4 and TMED9 decreases in the AD frontal cortex." (PMID 41103078, 2025).
pancreatic ductal adenocarcinoma (1 paper, 2025). An infiltrating adenocarcinoma that arises from the epithelial cells of the pancreas. "Furthermore, the results of proteomics-based survival analysis revealed that high TMED9 expression posed a risk factor for BRCA, GBM, HNSC, KIRC, LUSC, and pancreatic ductal adenocarcinoma (PDAC)." (PMID 40124371, 2025).
rectum adenocarcinoma (1 paper, 2025). An adenocarcinoma arising from the rectum. "Methylation analysis revealed that, except for rectum adenocarcinoma (READ), TMED9 exhibited lower methylation levels in most tumors compared to normal tissues." (PMID 40124371, 2025).
thymoma (1 paper, 2025). A neoplasm arising from the epithelial cells of the thymus. "TMED9 was positively associated with multiple genomic scores in KIRC, LIHC, thymoma (THYM), PAAD, and LGG, suggesting that higher expression of TMED9 may correlate with increased chromosomal instability in these patients." (PMID 40124371, 2025).
viral infections (1 paper, 2025). "Furthermore, TMED9 is involved in regulating viral infections and immune responses, thus highlighting its multifunctionality and significance in cell biology and disease." (PMID 40124371, 2025).